PRL (prolactin)
Diseases named in the same sentence as PRL in open-access papers (continued):
Sharing a sentence is not in itself a finding about the gene and the disease.
central nervous system tumors (2 papers, 2013 to 2019). "The meaning of intracellular presence of PRL may vary according to the malignant potentials of the tumors, and there is no data in the current literature on the possible causes for the presence of positive PRL immunohistochemistry in different types of CNS tumors." (PMID 23317095, 2013). "Thus, further studies are needed regarding the origin of this PRL identified with the immunohistochemistry technique and its true role in the pathogenesis of CNS tumors." (PMID 23317095, 2013). "The purpose of this study was to assess PRL expression in primary CNS tumors by real-time PCR and to correlate these findings with immunohistochemical hormone detection, contributing to a better understanding of the interrelationship between PRL and CNS tumors." (PMID 23317095, 2013). "Therefore, the absence of PRL expression by quantitative real-time PCR in human samples of different types of CNS tumors, the main finding of this study, is an unprecedented one." (PMID 23317095, 2013).
connective tissue disease (2 papers, 2017 to 2023). "Similarly, increased systemic prolactin concentrations during pregnancy have been linked to the release of proinflammatory cytokines and matrix metalloproteinases responsible for connective tissue disease from fibroblast-like cells." (PMID 37180059, 2023).
retinopathy (2 papers, 2014 to 2018). "Hence, the beneficial effect on retinopathy associated with pituitary stalk section or other alterations of pituitary function may have been, in part, also explained by a rise of retinal vasoinhibins as a consequence of an increased PRL secretion." (PMID 29896154, 2018).
electrolyte imbalance (1 paper, 2013). "Disturbances in the timing or amount of PRL released can lead to a variety of physiologic complications, including electrolyte imbalance, disruptions in growth and development, metabolic dysfunctions, behavioral disturbances, reproductive failure, or lactation failure." (PMID 23458715, 2013).
genetic disease (1 paper, 2016). "Here we observed a decrease in binding of PRL-2 when this corresponding threonine was mutated in CNNM3, suggesting a possible role for PRL in this CNNM-associated genetic disease." (PMID 26969161, 2016).
gynecological neoplasms (1 paper, 2021). "PRL promotes the initiation and progress of different gynecological neoplasms through different mechanisms." (PMID 34745013, 2021). "Considering the existing evidence of the critical role played by PRL in gynecological neoplasms, some therapeutical strategies are being investigated, such as the blockade of PRL/PRLR signaling." (PMID 34745013, 2021). "PRL exerts different biological effects that promote carcinogenesis and the progression of gynecological tumors, and its expression may induce several processes as survival, cellular proliferation, migration, invasion, metastasis, and resistance to treatment." (PMID 34745013, 2021).
reproductive diseases (1 paper, 2022). "In the past decades, accumulated evidence has shown that THs and reproductive hormones, including E2, progesterone, glucocorticoids, FSH, LH, prolactin, and oxytocin, jointly regulate the reproductive system processes, thus predetermining their involvement in the occurrence of reproductive diseases." (PMID 35269847, 2022).
PRL also shares sentences with these, for which no sentence is quoted: somatotroph adenomas (15 papers); Impotence (11); hypercortisolism (7); non-small cell lung carcinoma (7); Parkinsonism (6); psoriatic arthritis (6); toxoplasmosis (6); acute myeloid leukemia (5); somatotrophinoma (5); diabetic cardiomyopathy (4); gastric cancer (4); gastrinoma (4); goiter (4); hyperhomocysteinemia (4); Impaired glucose tolerance (4); kidney disease (4); rheumatic diseases (4); staphylococcus aureus infection (4); African trypanosomiasis (3); American trypanosomiasis (3); basal cell carcinoma (3); delirium (3); dry eye (3); Graves disease (3); herpesvirus infection (3); hypovitaminosis D (3); intrauterine growth restriction (3); Macroorchidism (3); nicotine addiction (3); pertussis (3).
A further 250 diseases each share a sentence with PRL in 3 papers or fewer.